EGFR (epidermal growth factor receptor)
Diseases named in the same sentence as EGFR in open-access papers (continued):
Sharing a sentence is not in itself a finding about the gene and the disease.
tumor (continued). "By influencing EGFR splicing, these ASOs aim to alter receptor expression or function in the cell membrane, thus potentially reducing tumor growth and improving responses to existing therapies." (PMID 40282505, 2025). "After retreatment with EGFR-TKIs, 13 patients experienced progression, 12/13 (85.7%) of whom underwent re-biopsy at that time; the tumor biopsy sites were the lung, lymph node, bone, and pleura in 2/14 (14.3%) patients each, and liver in 1/14 (6.7%)." (PMID 40704256, 2025). "Studies show that mTORC2 is significantly activated in EGFR-mutant non-small cell lung cancer (NSCLC), and its functional upregulation is closely associated with tumor invasiveness, epithelial-mesenchymal transition (EMT), and TKI resistance." (PMID 40510156, 2025). "Collectively, these results demonstrate that STARD4 exerts tumor-promoting effects through the activation of the EGFR/PI3K/AKT pathway in HCC cells." (PMID 40831538, 2025). "Inhibition of CMTM4 promoted efficacy of EGFR inhibitor to reduce tumor growth and prolong animal survival." (PMID 39948411, 2025). "After treatment with EGFR-TKIs, there was tumor progression, and a biopsy showed transformation to SCLC." (PMID 40134592, 2025). "Both SYVN1 and EGFR were expressed at higher levels in tumor tissues compared to normal tissues, as determined by Western blot." (PMID 40877231, 2025). "This dysregulation facilitates unchecked G1-S phase progression, promoting tumor proliferation and resistance to therapies such as EGFR inhibitors." (PMID 41375018, 2025). "Although patients treated with EGFR-TKIs experience extended progression-free survival and high tumor response rates, On-target and off-target resistance pose significant obstacles to this therapy." (PMID 40234395, 2025). "Quantitative analysis of tumor-specific mutations in ctDNA, such as single nucleotide variants in KRAS, NRAS, PIK3CA, BRAF, and EGFR, demonstrated over 80 % concordance with tumor tissue in patients with colorectal, lung, and breast cancers." (PMID 40144458, 2025). "Another example of an oncolytic virus targeting tumor markers involves the targeting of herpes simplex virus (HSV) to the epidermal growth factor receptor (EGFR)." (PMID 40697381, 2025). "Combining HER2 and EGFR with EpCAM in circulating tumor cell enrichment strategies enhances the capture of heterogeneous CTC populations, addressing the limitations of solely relying on EpCAM-based methods." (PMID 40076201, 2025). "Together, our findings demonstrate that although NS-LUAD tumours generally lack the high mutational burden KRAS mutant tumours, they require fewer copy number changes than their EGFR mutant counterparts to progress." (PMID 41509216, 2025). "Amivantamab acted by blocking the vital oncogenic pathways regulated by MET and EGFR, further recruiting immune cells to the tumor and enhancing tumor killing through mechanisms like ADCC." (PMID 40277763, 2025). "Increased activity of immune cells showing anti-tumor effects is a potential option to overcome EGFR-TKI resistance." (PMID 40002883, 2025). "Combining these with pan‐ERBB inhibitors enhances anti‐tumor effects in patient‐derived cellular RC models, showing its potential as an alternative to the combination with anti‐EGFR antibodies." (PMID 40956140, 2025). "This indicates the current clinical status of NSCLC is thatcompared with patients with normal EGFR, those with EGFR abnormalities exhibit more rapid disease progression, a greater likelihood of tumor cell invasion, and significantly more severe metastasis." (PMID 40732366, 2025).
tumor (continued). "Among the findings, the dataset highlighted significant associations between imaging features such as tumor size, texture, and [18F]FDG-PET uptake, with key oncogenic mutations (e.g., EGFR, KRAS, ALK) and survival outcomes." (PMID 40192792, 2025). "Although whole-exome sequencing (WES) has revealed critical molecular associations such as IDH-TERTp mutual exclusivity and EGFR-PTEN co-mutations, the clinical implications of genomic alterations depend substantially on the tumor type." (PMID 41377022, 2025). "Next, we investigated the functional significance of MIG6 as a tumor suppressor in the context of ligand‐induced EGFR‐mediated transformation." (PMID 39129344, 2025). "This integrated network revealed several pivotal signalling pathways pertinent to tumour development, encompassing EGFR, MAPK, WNT, cell cycle, DNA repair, TGF‐β, and ECM‐remodelling." (PMID 40038875, 2025). "A study on a liposome‐based epidermal growth factor receptor‐tyrosine kinase inhibitor (EGFR‐TKI) delivery system demonstrated significant tumor control and extended survival in animal models, showcasing potential for clinical trials." (PMID 40682256, 2025). "We further designed four bsAbs and characterized their abilities to engage with tumor cells, block EGFR signaling, and exert ADCC effects." (PMID 41291854, 2025). "Together, these data define a heterogeneous tumor composed of EGFR-amplified, PDFGRA-amplified, and MDM2::PDFGRA-harboring clones." (PMID 40819143, 2025). "Despite the identification of numerous molecular markers related to NSCLC, including EGFR mutations and ALK fusions, their expression is highly heterogeneous across patients and tumor subtypes, limiting their general applicability." (PMID 40055838, 2025). "EGFR is critical for tumor angiogenesis and cancer progression, but existing treatments like erlotinib face limitations such as acquired resistance and side effects." (PMID 40344575, 2025). "This suggests that while VPE is a useful imaging marker for assessing tumor burden and edema, its contribution to predicting EGFR-TKI response is limited, and further research is needed to explore its underlying biological mechanisms." (PMID 40438144, 2025). "For instance, several quinazoline-based compounds have been developed as epidermal growth factor receptor (EGFR) inhibitors for treating cancers, particularly non-small lung cancer cells, by impeding tumor growth and proliferation." (PMID 41009522, 2025). "In vitro MRI revealed strong contrast enhancement in EGFR-overexpressing tumor cells, while in vivo studies in xenograft models showed increased tumor uptake and prolonged contrast retention." (PMID 41325799, 2025). "In terms of certainty of evidence, the combination of CHIs and EGFR-TKIs potentially improved anti-tumor efficacy with uncertain results, compared to EGFR-TKIs alone (low certainty evidence)." (PMID 41347160, 2025). "Our group has previously reported enrichment of stem cell expression with the markers CD44, HLA-I, pan-CK, and p-EGFR in relapsed HNSCC after induction chemotherapy compared to the primary tumor." (PMID 40738059, 2025). "Epidermal growth factor receptor (EGFR)–tyrosine kinase inhibitor (TKI) resistance induces widespread changes across mutation profiles, cell populations and tumor-associated microenvironments." (PMID 40615564, 2025). "In terms of signaling pathways, cuproptosis was associated with multiple key tumor molecules, such as E2F and MYC target genes, MTORC1, EGFR, and SMAD signaling molecules." (PMID 41142609, 2025). "Monensin was also found to synergize with oxaliplatin and EGFR inhibitors and suppress proliferation and tumor growth using both in vitro an d in vivo models." (PMID 40862737, 2025). "These agents have the potential to differentiate active, EGFR-dependent tumor regions from areas rendered fibrotic by neoadjuvant treatments." (PMID 39796742, 2025).
tumor (continued). "Genomic profiling revealed EGFR and JUN amplifications with NCOR1 and PRKAR1A losses, alterations linked to aggressive tumor biology." (PMID 40979503, 2025). "EGFR-related epigenetic modifications are crucial for understanding the regulation of the EGFR gene and the mechanisms of tumor development and progression." (PMID 40486879, 2025). "The extracellular domain of EGFR present on the surface of tumor cells forms a highly immunogenic and tumor-specific epitope, making it a promising target for CAR-T therapy in NSCLC." (PMID 39995659, 2025). "Depletion of the tetra-transmembrane protein CMTM4 sensitizes tumor cells to EGFR inhibition and limits tumor growth by reducing the production of inflammatory cytokines and the recruitment of immune-suppressive cells." (PMID 39948411, 2025). "Instead, the absence of mutations in KRAS, NRAS, and BRAF and other mechanisms determine tumor dependency on EGFR signaling." (PMID 40940901, 2025). "To evaluate the statistical significance of achieving early tumor shrinkage, we first examined its implications in the anti-EGFR antibody group, in the bevacizumab group, and in the chemotherapy-alone group." (PMID 40280867, 2025). "EGFR, axillary stage, and tumor size showed prognostic significance in older women with TNBCs in univariate analysis." (PMID 40859044, 2025). "The superficial location of these tumors and their high EGFR expression levels make them ideal candidates for nanophotonic methods, enabling the detection of GNPs-EGFR reflections on tumor cells." (PMID 40095737, 2025). "The protein product of AREG is a ligand for the EGF/TGF-α receptor with connection to EMT, increased tumor cell migration and proliferation, and has been reported as a prognostic biomarker for treatment targeting EGFR in other cancer entities." (PMID 40082664, 2025). "For instance, eccDNA carrying amplified oncogenes such as MYC or EGFR contributes to tumor progression, clonal heterogeneity, and resistance to targeted therapies 63,84,85." (PMID 40521196, 2025). "EGFR signal transduction also contributes to tumor cell proliferation, resistance to apoptosis, angiogenesis, and metastasis (Chong and Jänne, 2013)." (PMID 39944617, 2025). "The biomarkers investigated included Programmed death-ligand 1 (PD-L1), Epidermal growth factor receptor (EGFR), Anaplastic lymphoma kinase (ALK), Kirsten rat sarcoma (KRAS), and others associated with tumor proliferation and therapeutic response." (PMID 40078179, 2025). "Preclinical studies demonstrated increased anti-tumor activity for this bispecific ADC compared to ADCs targeting either EGFR or HER3 with identical payload and linkers suggesting there is benefit to utilizing this bispecific design." (PMID 40160238, 2025). "Although advanced NSCLC patients harboring sensitizing EGFR mutations usually respond well to EGFR TKI during the first 1–1.5 year of treatment, most patients eventually develop resistance, leading to tumor regrowth or metastasis." (PMID 41142757, 2025). "Pathological eradication of EGFR positive tumor cells was observed in tumor biopsies after CAR-T cell treatment." (PMID 40624569, 2025). "EGF is a well-known growth factor that drives tumor cell proliferation and survival through its activation of the EGFR signaling pathway." (PMID 40584614, 2025). "This pathway sensitized tumor cells to EGFR blockade, and pharmacologic Hedgehog inhibition produced synergy with cetuximab in vitro." (PMID 41214389, 2025). "As prior research suggested, the inhibition or downregulation of EGFR or FGFR4 can lead to tumor suppression." (PMID 39858026, 2025).
tumor (continued). "EGFR-TKI therapy not only activates the immune response in EGFR-mutant NSCLC but also leads to increased immune cell infiltration within the tumor microenvironment following the onset of resistance." (PMID 40003951, 2025). "Recombinant anti-EGFR CAR-T cells have been developed with specific cytolytic activity against EGFR-positive tumor cells." (PMID 39995659, 2025). "Our findings more convincingly emphasize the potential of EGFR as a promising biomarker for predicting tumor immunotherapy response and prognosis across multiple cancer types." (PMID 40574864, 2025). "The PI3K pathway, a critical driver of tumor growth and survival, is frequently activated in GBM through mutations in genes like PTEN and EGFR." (PMID 40565099, 2025). "Previous studies have shown that circ-EGFR has dual effects on tumor initiation and progression in various cancers." (PMID 41214390, 2025). "Broad-spectrum Gln metabolic antagonists can inhibit the uptake and utilization of Gln by tumor cells, thereby suppressing tumor cell proliferation and increasing sensitivity to epidermal growth factor receptor tyrosine kinase inhibitors (EGFR-TKIs) in NSCLC." (PMID 40276500, 2025). "extended their observations by predicting, through molecular docking analysis, high association affinities between rTBL-1 and various aberrantly expressed N-glycans in the EGFR of tumor cells in a dependent manner on rTBL-1 CBP residues." (PMID 40006027, 2025). "Targeting the degradation of the EGFR protein demonstrates a significant inhibitory effect on tumor growth, potentially offering a new direction for the treatment of NSCLC." (PMID 40877231, 2025). "The recovered fluorescence intensity of this detector is found to be directly correlated with EGFR expression levels in cancer cells, indicating its potential for guiding tumour diagnosis and treatment." (PMID 40368641, 2025). "Aberrant FOXP3 expression facilitates tumor immune evasion and supports oncogenic activation of pathways such as EGFR." (PMID 41301890, 2025). "Anti-EGFR therapies can suppress tumor growth by selectively binding to the inactive configuration of EGFR’s extracellular domain, blocking the ligand-binding region and competing for receptor binding." (PMID 40598793, 2025). "BsAbs such as anti-CD3×anti-HER2/neu and/or anti-CD3×anti-EGFR have shown effectiveness in targeting GBM tumor cells expressing HER2/neu and EGFR, respectively." (PMID 41272822, 2025). "For example, therapies targeting cell signaling pathways (such as EGFR inhibitors) can be combined with those affecting tumor-stroma interactions, making it harder for cells to cooperate and evolve under treatment pressure." (PMID 40979445, 2025). "Surface modifications offer another targeting mechanism, where the display of tumor-specific peptides or antibody fragments, such as anti-EGFR scFv-on the bacterial surface promotes enhanced adhesion and infiltration into tumor tissues." (PMID 41394856, 2025). "Resistance of cetuximab was reversed in CRC from administering cetuximab-conjugated gold NPs, which increased EGFR endocytosis and degradation, leading to suppression of downstream signaling pathways and decreased tumor growth." (PMID 40777019, 2025). "To further elucidate the significance of these interactions, we focused on genes associated with tumor-related pathways such as Hedgehog, Notch, TGFβ, WNT, and EGFR signaling." (PMID 40557143, 2025). "It enables a deeper understanding of the mechanisms underlying EGFR-TKI resistance and its interactions with the tumor microenvironment, while uncovering the complexity of tumor heterogeneity during drug resistance." (PMID 40003951, 2025).
tumor (continued). "Nevertheless, our data reveals a compensatory mechanism wherein tumor cell survival is dependent on either EGFR or BRG1." (PMID 41514577, 2025). "In tumor cells, EGFR can be overexpressed, leading to reticular activating system (RAS) activation and the inhibition of PKR, which generally functions to limit viral synthesis." (PMID 41228258, 2025). "Given these high levels of evolutionary conservation of all proteins involved, we suggest that the induction of apoptosis by E-cad:EGFR:STAT complexes is likely to represent an important tumour suppressor in human epithelia." (PMID 40690511, 2025). "EGFR‐TKIs can competitively block the binding of ATP to mutant EGFR, to preventing the transmission of growth signals, and starving tumor cells, ultimately inhibiting the cancer cells." (PMID 39907159, 2025). "EGFR overexpression can activate downstream signalling pathways, resulting in uncontrolled cellular growth and increased tumor cell proliferation and metastasis, ultimately leading to tumorigenesis." (PMID 39813112, 2025). "This vaccine stimulates the production of antibodies that bind to EGF, thereby inhibiting the activation of EGFR and reducing tumor growth." (PMID 40859900, 2025). "Consistent with our in vitro data, FGFR inhibitors erdafitinib and infigratinib, and EGFR inhibitor gefitinib, enhanced alectinib sensitivity, delaying tumor remissions." (PMID 40313737, 2025). "For instance, loss of SMARCB1 leads to upregulation of EGFR and increased EGFR phosphorylation, thereby rendering rhabdoid tumor cells sensitive to EGFR-TKIs." (PMID 41514577, 2025). "On the other hand, studies also suggest targeting EGFR pathways given their participation in metabolic reprogramming, which is crucial for tumor growth and immune-escape mechanisms." (PMID 40075591, 2025). "Compared to the group receiving intravenous PCZ, the EGFR in the tumor tissue of the Gel@PCZ group exhibited membrane localization." (PMID 39560161, 2025). "Further caution is suggested by the observation that EGFR is associated with the concerning phenotype of CPI-induced hyper-progression, characterised by accelerated tumour growth and clinical deterioration." (PMID 40615716, 2025). "In LCSCs, miR-206 impeded tumor progression and chemoresistance by targeting the epidermal growth factor receptor (EGFR)." (PMID 40710326, 2025). "Recent studies indicate that EGFRvIII often functions in conjunction with EGFR, forming dimers that enhance tumor growth." (PMID 40331985, 2025). "The study identified α5-nAChR as an essential mediator for low-dose nicotine-dependent LUAD progression possibly through signaling crosstalk with EGFR, supporting the involvement of environmental smoke in tumor progression in LUAD patients." (PMID 40143965, 2025). "The oxidation of both EGFR and downstream phosphatases by ROS enhances EGFR-mediated signaling and contributes to tumor progression." (PMID 40563358, 2025). "In a previous study, Li and colleagues demonstrated that the mean tumor volume was significantly reduced within 40 days after treatment with EGFR-TKIs." (PMID 41383503, 2025). "Nanocarriers targeting specific receptors (TfR, LRP-1, CD44, EGFR) in brain and tumor tissues have demonstrated superior efficacy compared to conventional drugs in preclinical models." (PMID 40942013, 2025). "Clinically, DNAJC10 downregulation correlates with poor GBM survival, highlighting its tumor-suppressive role by disrupting XBP-1s–EGFR axis." (PMID 41191192, 2025). "Previously, the monomeric anti-EGFR Nanofitin B10 has shown high accumulation and broad diffusion in A431 tumor xenografts in immunodeficient mice, effectively targeting nearly all tumor cells as early as 90 min post-injection." (PMID 40305184, 2025). "PD-1 inhibitor plus radiotherapy can effectively inhibit the expression of EGFR in tumor tissues of BC patients and visibly improve the prognosis." (PMID 40819076, 2025).